TNF (tumor necrosis factor)
Diseases named in the same sentence as TNF in open-access papers (continued):
Sharing a sentence is not in itself a finding about the gene and the disease.
viral infection (continued). "The cytokines IFN-γ, IL-1β, and TNF have a critical role in promoting inflammation and several studies demonstrated as their suppression may lead to therapeutic effects in many inflammatory diseases, including viral infections." (PMID 33544720, 2021). "Notably, current pathological studies have shown that the severe patients infected by SARS-CoV-2 generally have higher plasma levels of IL-2, IL-6, IL-10, TNF-α, IFN-γ,41,43–45 implying a high risk of the inflammatory-associated cytokine storm after viral infection." (PMID 33895786, 2021). "Indeed, the majority of IL1β, IP10, and TNFα correlates described herein comport with a large body of literature indicating the mediating roles of proinflammatory cytokines in the pathogenesis of viral infections." (PMID 34067023, 2021). "Additionally, the recruitment of inflammatory cells by TNF-α and the increased susceptibility to further SARS-CoV-2 infection could exacerbate the viral infection and impair the metabolism, electrophysiology, and mechanical properties of the heart." (PMID 34576032, 2021). "In addition, excessive and uncontrolled production of TNF-α, IL-1β, IL-6, and other inflammatory cytokines by macrophages may result in serious systemic complications during viral infections such as tissue damage and septic shock." (PMID 34946051, 2021). "Since A179L was able to enhance TNF-α-mediated necroptosis, we speculate that A179L may facilitate virus release and spread at the late stage of the virus life cycle, if A179L can indeed promote necroptosis in a virus infection setting." (PMID 34960759, 2021). "Nonetheless, no increased risk for viral infections, i.e., respiratory infections such as influenza has been reported with the inhibition of TNF-α, IL-6, IL-17, or IL-23, which are the most frequent cytokine inhibitors currently used for the treatment of IMIDs13." (PMID 32709909, 2020). "Interestingly, virus infection can lead to an induction of the inflammation process, characterized by excessive production of nitric oxide (NO), Interleukin-1 (IL-1), Interleukin-6 (IL-6) and Tumor Necrosis Factor-α (TNF-α)." (PMID 32825564, 2020). "Viral infections induce a rapid and potent inflammatory response in different cell types, such as macrophages, fibroblastoid cells, and monocytes that is mediated by an early release of inflammatory cytokines, such as TNF-α, IL-6, and IL-8, and secretion of RANTES." (PMID 32463796, 2020). "The first barrier to viral infection is the innate immunity, which is comprised of cellular and soluble components including complement, immunoglobulin, erythrocyte and clotting factor binding (depending on species), and inflammatory cytokines (TNF-α, IL-1β, IL-6)." (PMID 30635014, 2019). "Interestingly, we observed an increase in the frequency of either CD4+ or CD8+ T cells producing TNF-α after immunization with the pE1D2 and challenge with DENV2, while lymphocytes from pcTPANS1-vaccinated animals maintained ordinary TNF-α production after virus infection." (PMID 31333657, 2019). "In addition to IFNs, pDC are also able to rapidly produce pro-inflammatory cytokines and chemokines upon viral infection; therefore we analyzed the secretion of the pro-inflammatory cytokines IL-6, TNF, and the chemokine IL-8 protein in the cell culture supernatants by ELISA." (PMID 30344524, 2018). "The mRNA levels of TNFα in the telencephalon rose rapidly in the buffer injected group up to 25.8-fold at day 3 and 94.6-fold at day 6 after infection compared to non-infected controls, which reflects the early activation of this pro-inflammatory cytokine as response to the virus infection." (PMID 27336830, 2016). "In rodent models, in utero viral infection mimicked by the administration of polyriboinosinic:polyribocytidylic acid (poly(I:C) resulted in the post-pubertal emergence of brain immune changes (specifically, IL-1β and TNF-α) and anxiety-related behaviors in the offspring." (PMID 27244231, 2016).
viral infection (continued). "However, specific biomarkers for the 2 viral infections could also be distinguished (TNF-α for DENV and IFN-α for CHIKV)." (PMID 25635123, 2015). "Moreover, proinflammatory cytokines, such as IL-1, IL-8, CXCL10, IL-6, and TNF-α, are known to be released within hours after inflammation challenge and serve as unspecific alarm signals, as they are released during viral infection, asthma and atopic dermatitis." (PMID 21909400, 2011). "Thus, our data indicate that uncontrolled production of TNFα in the CNS upon viral infection may consequentially contribute to oligodendrocyte death and demyelination." (PMID 21812954, 2011). "This cellular activation leads to an earlier and amplified production of proinflammatory cytokines, such as IL‐6, TNF‐α, and IFN‐γ, which are mobilized to suppress viral infection." (PMID 41488232, 2026). "Particular attention in this article is devoted to the role of cytokines (IL-6, TNF-α, and IFN-γ) in the pathogenesis of hyperacute viral infection." (PMID 42196581, 2026). "The best-studied stimulus for the activation of necroptosis is Tumor Necrosis Factor (TNF); however, necroptosis can also be initiated by other members of the TNF death ligand family, interferons, TLR signalling and viral infection." (PMID 39705008, 2025). "At 14 dpi, dynamics shifted and WT mice showed a statistical trend towards an increase of TNF-α mRNA expression compared to CLEC12A−/− mice (p = 0.05), likely related to prolonged virus infection in WT mice." (PMID 41214106, 2025). "In cases of viral infections, SK1 expression is induced via TNF-α signaling and regulated by the ERK/AKT pathway (69, –, 71)." (PMID 39791903, 2025). "ST3GAL2 resists viral infection by downregulating pro-inflammatory cytokines (IL-6, IL-18, IL-1β, IFN-β, TNF-α) and upregulating anti-inflammatory cytokines (IL-4, IL-10, IL-13)." (PMID 40755778, 2025). "Mechanistically, neurotropic viral infections such as PRV are known to activate the pathway, driving the transcription of pro-inflammatory cytokines (e.g., TNF-α, IL-6), while excessive ROS production further amplifies inflammation." (PMID 41180235, 2025). "This includes TH1 cells, which respond to viral infection with a distinct cytokine response that typically comprises IFN‐γ and TNF‐α, and this is also the case for BKPyV infection." (PMID 39949253, 2025). "These cultured MPs are, therefore, far from being able to facilitate a functional TL profile compatible with the control of viral infection, which would involve the secretion of IFNγ, IL2 and TNFα." (PMID 40181981, 2025). "Necroptosis, on the other hand, can be initiated by various stimuli, including tumor necrosis factor (TNF), Fas ligand, and certain viral infections, particularly in contexts where caspase activity is inhibited or absent." (PMID 40893939, 2025). "Particularly, CD8+ T cells are essential in protecting from WNV infection, and they control viral infections by triggering apoptosis of infected cells through perforin- or Fas ligand-dependent pathways or producing antiviral cytokines (e.g., IFN-γ and TNF-α)." (PMID 40632810, 2025). "Superantigens reduce cutaneous interferon-γ and tumor necrosis factor-α (TNF-α) production, which are crucial for cellular protection against bacterial and viral infections." (PMID 39918744, 2025). "CD8+ T cells control viral infections by triggering apoptosis of infected cells via perforin or Fas ligand-dependent pathways or producing antiviral cytokines (e.g., IFN-γ and TNF-α)." (PMID 40632810, 2025). "This shift allows them to sustain the production of pro-inflammatory cytokines such as interferon-gamma (IFNγ), tumor necrosis factor (TNF), and interleukin-2 (IL-2), which drive immune responses against viral infections." (PMID 40453076, 2025). "Most cancer cells have impaired mechanisms for defending against viral infections, such as the interferon (IFN) signaling or tumor necrosis factor (TNF) pathway." (PMID 40005517, 2025).
viral infection (continued). "Of note, in DF-1 cells, the virus expressing NS100 stimulated a higher level of TNF-α RNA than WT NS1 at 24 hpi, although IFN-β and Mx levels remained lower levels under NS100 virus than RG-AIV-WT virus infection at 12 hpi." (PMID 40899958, 2025). "Importantly, viral infections may trigger senescence either directly, through mechanisms such as DNA damage, or indirectly via prolonged exposure to cytokines like interferons and tumor necrosis factor-alpha." (PMID 40661646, 2025). "Viral infection pathways (e.g., Influenza A, Coronavirus disease COVID-19) and innate immune signaling cascades (NOD-like receptor, Toll-like receptor, and TNF signaling) were also prominently enriched." (PMID 41303731, 2025). "NLRP4 can negatively regulate Tumor Necrosis Factor (TNF) and IL-1β-induced NF-κB activation, and can also negatively regulate type I interferon signaling in response to dsRNA, DNA, or viral infection, and regulate autophagy in response to bacterial infection." (PMID 41463370, 2025). "Acute Th1-mediated inflammatory responses following viral infections often involve increased production of both IFN-γ and TNF-α." (PMID 39052685, 2024). "Thus, based on the fact that we could not observe a virus-induced induction of FAT10 expression in A549 cells, we speculate that the inflammatory microenvironment that accompanies the viral infection in vivo (which includes TNF and IFNγ) stimulates FAT10 expression." (PMID 37940187, 2024). "In the current study, an intense immunoexpression of IL-1β and TNF-α was also observed in the acinar and GCT cells of the infected SMGs, confirming a specific “inflammatory response” of these epithelial cells to the viral infection." (PMID 38999930, 2024). "Cytokines and inflammatory chemokines (IL-1ra, IL-6, TNF-α, IL-8, G-CSF, MCP-1/CCL2, and PDGF) have been shown to be elevated in the CSF samples of pediatric patients in whom viral infection led to the SIDS in comparison with the control groups." (PMID 38675861, 2024). "Nevertheless, expression of IL-6, TNF-α, and CCL-2 in the lung and brain increased with viral infection." (PMID 39077737, 2024). "TNF can have an anti-inflammatory effect in specific settings of CD8+ T cell activity (e.g., apoptosis induction after a viral infection)." (PMID 39466773, 2024). "To illustrate, the viral infection results in CD8+ T-lymphocytosis, releasing a pool of cytokines, including interferon-gamma, interleukin-2, and TNF-alpha." (PMID 38883093, 2024). "Tumour necrosis factor alpha (TNF-α) is a member of the 19 TNF superfamily that is secreted in the brain in response to pathogen invasions, such as bacterial and viral infections, as well as brain injuries." (PMID 38494488, 2024). "Necroptosis can be triggered by Toll-like receptor activation, ROS accumulation in mitochondria, tumor necrosis factor-α (TNF-α), and viral infection." (PMID 38729953, 2024). "In response to viral infection, immune cells secrete various pro-inflammatory cytokines including IL-1, IL-6, interferon (IFN)-γ, and tumor necrosis factor (TNF), shifting the metabolic state toward aerobic glycolysis." (PMID 38965547, 2024). "In the late phase of acute viral infection, type II IFNs including IFN-γ and several other cytokines (including TNF-α and IL-10) are released by CD8+ T cells, strongly upregulating PD-L1 on various cell types." (PMID 38745748, 2024). "It is presumed that emodin can enhance the inflammatory response and inhibit virus replication by increasing the levels of TNF-α and IFN-γ in the early stages of virus infection." (PMID 37764342, 2023). "IKBKE-deficient mice are viable, although they are hypersusceptible to some viral infections, whereas TBK1-knockout mice die at embryonic day 15 from TNF-induced apoptosis in the liver." (PMID 37937644, 2023). "Whereas Ubc9 depletion increases protective IFNγ responses to viral infections, TAK981 increases TNFα anti-bacterial responses." (PMID 37520526, 2023).
viral infection (continued). "Many viral infections, including HSV-1, RSV, and SARS-CoV-2 infection enhances the production of several cytokines, such as IL-6, IL-8, and TNF-a in epithelial cells." (PMID 37112969, 2023). "Necroptosis can be induced by a variety of stimulation such as activation of Toll-like receptor (TLR), tumor necrosis factor (TNF), cellular stresses, and microbial or viral infection." (PMID 37854679, 2023). "In the case of viral infections, elevated levels of various inflammatory cytokines, including IL-1β, IL-6, IL-7, IL-17, IFN-γ, IL-8, TNFα, and GM-CSF are observed, alongside IL-4 and IL-5." (PMID 37692890, 2023). "Lgals3bp expression is induced by viral infection and upon exposure to pro-inflammatory, such as IFN-α, IFN-β, IFN-γ, and TNF-α." (PMID 37491623, 2023). "TNF-α, IFN-γ and IL-6, as important proinflammatory cytokines, can help the body fight a viral infection and prevent tissue damage by regulating the inflammatory response." (PMID 37508153, 2023). "TNF-α, IFN-γ, and IL-6, as important proinflammatory cytokines, can help the body fight viral infection and tissue damage by regulating the inflammatory response." (PMID 37764342, 2023). "Upon viral infection or in response to type I and type III IFNs, LPS, TNF-α, or genotoxic stress, the USP18 is rapidly and strongly upregulated after these inflammatory stimuli." (PMID 37658402, 2023). "NK cells are critically important in the early immune response for the clearance of viral infections, mainly through the production of IFN-γ and TNF-α." (PMID 37063898, 2023). "GAS6 mRNA was decreased in the MSCs stimulated with recombinant IL-1β, TNF-α, TGFβ1 (produced by MSC), and PDGBB (produced by endothelial cells) at 6 h, while poly I:C, known to mimic viral infections, increased GAS6 expression." (PMID 37958918, 2023). "Conversely, GSH treatment has been found to reduce viral infection and viral load, inhibit pro-inflammatory cytokine production (e.g., IL6, IL8, and TNFα), oxidative stress, and thrombosis, as well as potentially enhance immune function." (PMID 37534078, 2023). "For example, Pb suppresses the functions of IgM-type B cells, helper T cells, TNFα, IFN-γ, and IL-2, which contribute to defense against viral infections, but enhances the functions of IL-1 and 8, which induce inflammatory responses." (PMID 37508115, 2023). "KEGG enrichment analysis revealed that LWDH exerts its therapeutic effects on CKD by regulating the AGE-RAGE signaling pathway, IL-17 signaling pathway, TNF signaling pathway, HIF-1 signaling pathway, and multiple viral infections." (PMID 37171332, 2023). "Interestingly, we observed a negative correlation between levels of TNFα in the plasma and frequency of unswitched memory cells providing evidence that TNFα may promote the loss of unswitched memory B cells with viral infection." (PMID 37638016, 2023). "The “cytokine storm”, an increased release of tumor necrosis factor (TNF), interferon-gamma (IFN-γ), interleukins, and other cytokines, is one of the main characteristics of severe viral infections, including SARS and COVID-19 disease." (PMID 36145270, 2022). "This subsequently triggers the release of a series of pro-inflammatory factors such as tumor necrosis factor-alpha (TNF-α), and interleukin 1&6 (IL-1, IL-6), which together facilitate the early controlling of the viral infection." (PMID 36578545, 2022). "TNF receptors, TNF-α, CD8+ T cells, and NK cells protect against viral infection and can also play a role in immunopathology due to their contact-dependent effector actions." (PMID 36685920, 2022). "In T cell exhaustion, loss of individual effector molecules follows the hierarchical order of IL-2, TNF-α, IFN-γ, and proliferation during the establishment of chronic viral infection." (PMID 35040433, 2022).
viral infection (continued). "Upon activation, MAIT cells secrete effector molecules, including interferon-γ (IFN-γ), tumor necrosis factor-α (TNF-α), granzyme B, and granulysin to respond to the signaling aroused by viral infection." (PMID 35619176, 2022). "Part of this genetic locus, including Samd9l, was also reported to modulate proinflammatory cytokines, including TNF-α and IFN-α, after viral infections." (PMID 36074606, 2022). "The release of inflammatory cytokines, e.g., interleukin (IL)-6, IL-1β, tumor necrosis factor (TNF)-α, and IL-8, tend to rise during this viral infection, determining severe inflammatory complications." (PMID 35464396, 2022). "We validated this finding through RT-qPCR, confirming that the expression of the proinflammatory factors IL-1β, CCL4, TNF and CXCL8 decreased progressively with viral infection." (PMID 36544767, 2022). "As expected, HSV-1 infection induced a substantial increase in IRF-1, TNF-α, and IL-15 mRNA levels in the wild-type Vero cell line, increasing IRF-1 up to 30-fold 2 days after viral infection." (PMID 35897807, 2022). "Cytokines associated with lung injuries, such as IL-1 and TNF-α could induce the production of several chemokines, such as CCL2, CCL3, CCL5, and CXCL8, culminating in a cytokine-to-chemokine-to-cytokine signaling cascade through inflammatory response to the viral infection." (PMID 36685603, 2022). "Overall, pro-inflammatory cytokines, such as TNF-α, IL-6, type I IFN, and IL-1β, are common in viral infections." (PMID 35284964, 2022). "qRT-PCR analyzed the immune genes, including IL-1β, TRAF3, TNF-α, and TLR2 expression levels in JFSP cells after virus infection." (PMID 36552207, 2022). "The Th1 cytokines, which are interferon-γ (IFN-γ), interleukin 12 (IL12) and tumor necrosis factor-α (TNF-α) and Th17 cytokines (IL-17, IL-21, IL-22 and IL-23) play a role in combating bacterial and viral infections." (PMID 36359526, 2022). "Among them, Toll and Imd signaling, TNF signaling, NF−κB signaling and MAPK signaling pathways were related to virus infection." (PMID 36298658, 2022). "It is well known that the damage to endothelial cells after viral infection and/or activation of endothelium by pro-inflammatory cytokines, such as IL-1β, IL-6, IFN-γ, IL-8 and TNF-α induces platelets and monocyte aggregation in the vascular wall." (PMID 36291697, 2022). "CCL20/MIP-3α is a strong chemotactic factor for lymphocytes, while a weak factor for neutrophils, that is upregulated by IFN-γ, tumor necrosis factor (TNF) and lipopolysaccharide, inducing a marked lung damage upon viral infection." (PMID 34851149, 2022). "The analysis of the KEGG pathway was primarily related to TNF, IL-17, HIF-1, MAPK, AGE-RAGE, virus infection, and cancer signaling pathways." (PMID 36118092, 2022). "Virus infection stimulated the production of inflammatory and antiviral mediators, including interleukin (IL)-6, CXCL-8, tumor necrosis factor (TNF)-α, and type I/III interferons." (PMID 35265536, 2022). "The well-known role of TNF-α in the control of viral infection and the strong IFN-γ−/TNF-α+ response observed for SRAS-CoV-2-specific CD4+ T-cells described here would be in favor of such a possibility." (PMID 35335079, 2022). "Liu, Zhang52 reported that NF-kB was activated by several stimuli including TNF-α, interferon-gamma (IFN-γ), interleukins, bacterial and viral infection." (PMID 35654991, 2022). "As innate immune cells, NK cells can rapidly respond to viral infections by secreting IFN- and TNF- cytokines to upregulate the defense mechanism." (PMID 34367128, 2021). "In contrast to the well-defined LPS-induced cytokine response of the two MΦ subsets, the role of the different phenotypes in mediating TNF-α and IFN release upon viral infection has been less extensively studied." (PMID 34975859, 2021).